TRMT61B (tRNA methyltransferase 61B)
Description:
Methyltransferase that catalyzes the formation of N(1)- methyladenine at position 58 (m1A58) in various tRNAs in mitochondrion, including tRNA(Leu) (deciphering codons UUA or UUG), tRNA(Lys) and tRNA(Ser) (deciphering codons UCA, UCU, UCG or UCC). Catalyzes the formation of 1-methyladenosine at position 947 of mitochondrial 16S ribosomal RNA and this modification is most likely important for mitoribosomal structure and function. In addition to tRNA N(1)-methyltransferase activity, also acts as a mRNA N(1)-methyltransferase by mediating methylation of adenosine residues at the N(1) position of MT-ND5 mRNA, leading to interfere with mitochondrial translation.
Synonyms: FLJ20628
Tractability: PROTAC: ubiquitination databases record sites on it; its protein half-life has been measured.
Gene: Protein-coding gene on chromosome 2 (28,849,793 to 28,870,392, reverse strand). Ensembl gene ENSG00000171103.
Subcellular location: Mitochondrion matrix
Subcellular location (Human Protein Atlas): Cytosol
Pathways (Reactome):
Metabolism of RNA: Mitochondrial mRNA modification; tRNA modification in the mitochondrion
Gene Ontology:
Molecular function: mRNA (adenine-N1-)-methyltransferase activity; protein binding; rRNA (adenine) methyltransferase activity; tRNA (adenine(58)-N1)-methyltransferase activity; tRNA (adenine) methyltransferase activity
Biological process: mitochondrial tRNA processing; mRNA processing; tRNA methylation
Cellular component: mitochondrial matrix; mitochondrion; tRNA (m1A) methyltransferase complex
Genetic constraint (gnomAD): Loss-of-function variants: 36 observed, 35.59 expected, observed/expected ratio (o/e) 1.01, 90% interval 0.77 to 1.34. The upper end of that interval is the gene's LOEUF score, 1.34, which puts it in group 5 of 6, group 1 being the genes least tolerant of losing a copy. Missense variants: 531 observed, 496.5 expected, observed/expected ratio (o/e) 1.07, 90% interval 1 to 1.15. Synonymous variants: 187 observed, 198.42 expected, observed/expected ratio (o/e) 0.94, 90% interval 0.84 to 1.06.
Homologues: Orthologues: chimpanzee TRMT61B (99% identical), macaque TRMT61B (90% identical), pig TRMT61B (75% identical), guinea pig TRMT61B (71% identical), tropical clawed frog trmt61b (40% identical), zebrafish trmt61b (33% identical), Drosophila melanogaster Trmt61 (13% identical), Caenorhabditis elegans W02A11.1 (10% identical). Paralogues in human: TRMT61A (12% identical).
Diseases named in the same sentence as TRMT61B in open-access papers:
TRMT61B is named in the same sentence as 15 diseases in open-access papers, as found by Europe PMC text mining. Sharing a sentence is not in itself a finding about the gene and the disease. The quoted sentences say what the papers report.
Alzheimer disease (4 papers, 2016 to 2023). A progressive, neurodegenerative disease characterized by loss of function and death of nerve cells in several areas of the brain leading to loss of cognitive function such as memory and language. "TRMT61B was responsible for 1-methyladenosine of mitochondrial tRNA and participated in altered gene expression which involved in mitochondrial processes in Alzheimer’s disease." (PMID 36765416, 2023). "TRMT61B is shown to be involved in RNA modifications in many tissues that are related to a variety of complex diseases and is differentially expressed in astrocytes in relation to Alzheimer’s disease." (PMID 37192378, 2023). "Finally, it is intriguing that the expression of TRMT61B is altered in Alzheimer’s disease, thus suggesting altered levels of mitochondrial tRNA and rRNA modifications in this disease." (PMID 27631568, 2016).
glioma (3 papers, 2021 to 2024). A benign or malignant brain and spinal cord tumor that arises from glial cells (astrocytes, oligodendrocytes, ependymal cells). "Kaplan–Meier survival curves showed that overexpression of TRMT61B, TRMT6, TRMT61A, YTHDFs, ALKBH1, and ALKBH3 was significantly associated with poor overall survival in glioma." (PMID 34631793, 2021). "Then we found that overexpression of TRMT61B, TRMT6, TRMT61A, YTHDFs, ALKBH1, and ALKBH3 was significantly associated with poor overall survival in glioma." (PMID 34631793, 2021). "Subsequently, IHC images selected from the HPA database also proved that TRMT6, TRMT61B, and YTHDF2 were upregulated in glioma tissues." (PMID 34631793, 2021).
melanoma (3 papers, 2023 to 2026). A malignant, usually aggressive tumor composed of atypical, neoplastic melanocytes. "Recently, TRMT61B was found to be associated with high levels of aneuploidy, and its knockdown led to senescence and apoptosis of melanoma cell lines." (PMID 37531210, 2023). "TRMT61B knockdown leads to senescence and apoptosis of melanoma cell lines." (PMID 37531210, 2023). "In addition, the role of TRMT61B in hepatoblastoma and melanoma has been preliminarily revealed: in the SK-MEL-103 melanoma cell line, TRMT61B knockout significantly inhibited tumor growth and metastasis and prolonged the survival of mice." (PMID 41501031, 2026). "Additionally, the absence of TRMT61B can lead to senescence in melanoma cell with low levels of aneuploidy, while in melanoma cell with high levels of aneuploidy, it can lead to apoptosis." (PMID 39687616, 2024).
breast carcinoma (2 papers, 2016 to 2026). "For example, the TRMT61B gene may be related to susceptibility to breast cancer, but its specific mechanism of action in breast cancer still needs to be clarified through further research." (PMID 41501031, 2026). "Thus, modulation of TRMT61B expression may contribute in part to the risk of breast cancer in this region." (PMID 27117709, 2016). "In addition, Pol2 ChIA-PET in MCF7 breast cancer cells revealed an interaction between Region 1 and the promoter of TRMT61B, which had the strongest eQTL signal in the locus." (PMID 27117709, 2016). "Thus, WDR43 and TRMT61B may be regulated by interactions of enhancers in WDR43 with the core WDR43 and TRMT61B promoters and may jointly influence breast cancer risk in this region." (PMID 27117709, 2016).
hepatoblastoma (2 papers, 2023 to 2026). Hepatoblastoma (HB) is a malignant hepatic tumor and is the most common pediatric liver cancer. "Given the importance of m1A in tumorigenesis and the impacts of TRMT61B gene variants on m1A RNA levels, it is necessary to explore the association between TRMT61B gene SNPs and hepatoblastoma susceptibility." (PMID 37531210, 2023). "Collectively, we identified TRMT61B as a high-quality hepatoblastoma gene, and the roles of its genetic variant in disease susceptibility deserve further attention." (PMID 37531210, 2023). "Some evidence has shown that genetic variants of TRMT61B might contribute to cancer susceptibility; however, its roles in hepatoblastoma are unknown." (PMID 37531210, 2023). "The roles of TRMT61B genetic variants in hepatoblastoma have not been reported." (PMID 37531210, 2023).
breast tumours (1 paper, 2016). "In the 2p23.2 locus, the strongest cis eQTL associations for 735 TCGA breast tumours (BC765) involved TRMT61B expression." (PMID 27117709, 2016).
gastric cancer (1 paper, 2025). A primary or metastatic malignant neoplasm involving the stomach. "TRMT61B has been shown to be differentially expressed in various tumor types, including gastric cancer and highly aneuploid tumors, and is associated with poor clinical prognosis in gastric cancer patients." (PMID 40597017, 2025).
tumor (7 papers, 2021 to 2026). "Similarly, in zebrafish embryos and nude mouse models, TRMT61B inhibition slowed tumor cell proliferation." (PMID 41501031, 2026). "Small-molecule inhibitors targeting TRMT61B’s methyltransferase activity could disrupt mitochondrial function and suppress tumor growth, but further studies are needed to evaluate their therapeutic efficacy." (PMID 40597017, 2025). "TRMT61B was moderately expressed in both tumor and normal samples." (PMID 34777359, 2021). "Among the regulatory genes, ALKBH1 and ALKBH3, which are methylation erasers, were upregulated and TRMT10C, TRMT6, TRMT61B, YTHDF2, and YTHDF3 were downregulated in tumor samples in comparison to normal tissues." (PMID 37679761, 2023). "The staining intensity of TRMT61B, TRMT10C and ALKBH1 in tumor tissue is higher than that in normal kidney tissue." (PMID 37542141, 2023). "In terms of mRNA levels, TRMT6, TRMT61A, TRMT61B, TRMT10C, YTHDF1 and YTHDF2 YTHDF3 were overexpressed in tumor sample." (PMID 34777359, 2021). "TRMT61A, TRMT61B, YTHDF1 and YTHDF3 mRNAs were higher in tumor tissues, but protein expression was weaker or not apparently distinct between tumor and normal samples." (PMID 34777359, 2021).
cancer (3 papers, 2023 to 2024). A tumor composed of atypical neoplastic, often pleomorphic cells that invade other tissues. "Further analyses revealed that RAB42 overexpression is positively correlated with writer genes TRMT10C, TRMT61B and reader gene DNMT3B in most cancers." (PMID 39101146, 2024).
TRMT61B also shares sentences with these, for which no sentence is quoted: colon cancer (1 paper); lung adenocarcinoma (1); mitochondrial disease (1); Obesity (1); ovarian carcinoma (1); Sepsis (1).